ACSL3 (acyl-CoA synthetase long chain family member 3)
Diseases named in the same sentence as ACSL3 in open-access papers (continued):
Sharing a sentence is not in itself a finding about the gene and the disease.
lung adenocarcinoma (8 papers, 2020 to 2025). A carcinoma that arises from the lung and is characterized by the presence of malignant glandular epithelial cells. "The expression levels of ACAT1 and ACSL3 in tissues derived from normal lung and lung adenocarcinoma (LUAD) tissues were compared by qRT‐PCR." (PMID 39323079, 2024). "In addition, ten genes (such as anti-ACSL3 antibody (ACSL3), GPX4, and SLC7A11) associated with ferroptosis have been postulated to have regulatory roles in lung adenocarcinoma." (PMID 38590315, 2024). "In addition to ACSL3, ACSL4 has been shown to co-regulate ferroptosis in lung adenocarcinoma in conjunction with lysophosphatidylcholine acyltransferase 3 (LPCAT3) and yes-associated protein (YAP)." (PMID 41288931, 2025). "Our study identified a novel m6A-related ferroptosis-associated six-gene signature (comprising SLC2A1, HERPUD1, EIF2S1, ACSL3, NCOA4, and CISD1) for predicting lung adenocarcinoma prognosis, yielding a useful prognostic biomarker and potential therapeutic target." (PMID 37072786, 2023). "IGF2BP3 could stabilize a spectrum of anti-ferroptosis mRNA, including glutathione peroxidase 4 (GPX4), solute carrier family 3 member 2 (SLC3A2), acyl-CoA synthetase long chain family member 3 (ACSL3), and ferritin heavy chain 1 (FTH1), to inhibit ferroptosis in lung adenocarcinoma cells." (PMID 37554271, 2023).
pancreatic cancer (8 papers, 2016 to 2025). "Our results indicate that in pancreatic cancer cells ACSL3 loss-of-function impairs extracellularly derived FAs cellular retention, reduces cell proliferation and variably induces cell death." (PMID 34998392, 2022). "The simultaneous upregulation of GPX4 and ACSL3 prevents lipid peroxidation and ultimately protects pancreatic cancer cells from ferroptosis bothin vitro andin vivo." (PMID 39396119, 2024). "The differential induction of cell death in pancreatic cancer cell lines upon extracellular lipid restriction, either by ACSL3 knockdown or serum lipid depletion, underscores the heterogeneity of human pancreatic tumors." (PMID 34998392, 2022). "In mouse pancreatic cancer, Acsl3 deletion triggered reduced tumor cell proliferation, in part by impairing the production of the pro-fibrotic plasminogen activator inhibitor-1 (PAI-1), decreasing desmoplasia and immunosuppression." (PMID 34998392, 2022). "To assess the expression level of ACSL3 in human pancreatic cancer, we examined publicly available human patient-derived data from the Gene Expression Omnibus (GEO) database (subset GSE71729)." (PMID 33127675, 2020). "Future studies are warranted to understand the role of ACSL3 in TGF-β signaling pathway in pancreatic cancer." (PMID 33127675, 2020). "We then aimed to evaluate whether suppression of ACSL3 affects human pancreatic cancer cell proliferation." (PMID 34998392, 2022). "ACSL3 is overexpressed in human and mouse pancreatic cancer tissue compared to healthy pancreas." (PMID 34998392, 2022). "For example, the simultaneous upregulation of GPX4 and ACSL3 prevents lipid peroxidation and protects pancreatic cancer cells from ferroptosis both in vitro and in vivo, as shown through IL15RA-STAT3-GPX4/ACSL3 signaling." (PMID 41226317, 2025). "In conclusion, PSCs protect pancreatic cancer cells from ferroptosis by secretion of IL15, which further activates the IL15R-STAT3-GPX4/ACSL3 axis in a paracrine way." (PMID 39396119, 2024). "The upregulated levels of IL15RA, ACSL3 and GPX4 in pancreatic cancer cells were verified by qRT-PCR and western blot analysis." (PMID 39396119, 2024). "Therefore, we performed immunoblot analysis to assess the degradation of p62 on pancreatic cancer tissue from KPC;Acsl3+/+ and KPC;Acsl3−/− mice." (PMID 34998392, 2022). "Furthermore, we used small interfering RNA to silenceIL15 in activated PSCs and detected whether it affects the protein level of pancreatic cancer cells.IL15 silencing decreased IL15RA, p-STAT3, GPX4 and ACSL3 expression levels." (PMID 39396119, 2024). "We recently showed that the acyl-coA synthetase long chain 3 (ACSL3), an enzyme that promotes the activation and retention of extracellular unsaturated FAs by converting them into hydrophilic fatty acyl-CoA esters that cannot exit cells, is overexpressed in KRAS-driven lung and pancreatic cancer." (PMID 34998392, 2022).
clear cell renal cell carcinoma (6 papers, 2022 to 2024). "In clear cell renal cell carcinoma, acyl-CoA synthetase 3 (ACSL3) could regulate ferroptosis susceptibility in a manner dependent on lipid droplet accumulation by metabolizing exogenously derived lipids." (PMID 36942991, 2023). "ACSL3 also regulates the accumulation of lipid droplets in clear cell renal cell carcinoma (ccRCC) and modulates the sensitivity of ccRCC to ferroptosis in a manner dependent on the composition of exogenous fatty acids." (PMID 39285846, 2024). "We discovered that ACSL3 is substantially associated with the immune checkpoint inhibitors PD-1, PD-L1, CTLA4, LAG3, and HAVCR2 in renal clear cell carcinoma." (PMID 36338658, 2022). "The purpose of this research was to figure out the ACSL3's prognostic value and mechanism in clear cell renal cell carcinoma (ccRCC)." (PMID 36338658, 2022). "ACSL3 expression was lower in renal clear cell carcinoma cells, including 786O and A498, compared to normal HK-2 cells, as shown by the data." (PMID 36338658, 2022).
gastric cancer (5 papers, 2021 to 2025). A primary or metastatic malignant neoplasm involving the stomach. "The activation of MAT2A expression in gastric cancer protects tumoral cells from ferroptosis, by increasing methylation of histone H3 of acyl-CoA synthetase long chain family member 3 (ACSL3) promoter in a SAMe-dependent manner." (PMID 39941901, 2025). "Moreover, MAT2A can produce SAM, which trimethylates the promoter of ACSL3, leading to ACSL3 upregulation and ferroptosis resistance in gastric cancer." (PMID 38459004, 2024).
ovarian carcinoma (5 papers, 2016 to 2024). A malignant neoplasm originating from the surface ovarian epithelium. "Recent studies have demonstrated significant up-regulation of ACSL1 and ACSL3 protein levels in highly metastatic ovarian cancer cell lines, with gene expression associated with increased metastatic capacity and poor survival prognosis." (PMID 38957470, 2024). "Interestingly, in ovarian cancer, however, the homozygous deletion of ACSL3 is significantly related to the increased risk of recurrence in patients treated with adjuvant chemotherapy, suggesting that ACSL3 may be cancer-specific and possess complicate functions." (PMID 35223835, 2022). "On the other hand, ACSL3 may be considered as a potential tumor suppressor gene in ovarian cancer development." (PMID 27171439, 2016). "The OS of ovarian cancer patients prolonged with the high-expression of ATG7, G6PD, SLC3A2, MAP1LC3C and PTGS2, but shrank with the increased expression of NFS1, VDAC2, ACSL3." (PMID 35039008, 2022).
bladder cancer (3 papers, 2022 to 2026). "METTL7B expression promotes m6A modification on Acyl-CoA Synthetase Long Chain Family Member 3 (ACSL3) mRNA, thereby reducing ACSL3 gene expression and ultimately inhibiting ferroptosis in bladder cancer." (PMID 41194259, 2025). "In addition, rescue assay results indicated that ACSL3 mediated the roles of NT5DC2 in suppressing ferroptosis of bladder cancer cells." (PMID 41974665, 2026). "Collectively, our findings suggest that NT5DC2/ACSL3 plays a critical role in bladder cancer progression and ferroptosis regulation, suggesting that NT5DC2/ACSL3 is a potential therapeutic target for bladder cancer treatment." (PMID 41974665, 2026).
diabetes (3 papers, 2018 to 2022). "Specifically, it should be noted that ABCG1, ABCA1 and ACSL3 were negatively, while KAT2B positively, associated with all signatures of statin use, CpG methylation and diabetes risk/status." (PMID 32612641, 2020).
liver disease (3 papers, 2023 to 2026). "ACSL3 integrates metabolic and stress pathways that shape the liver disease trajectory by coupling lipid droplet biogenesis with apoptosis and inflammatory niche formation." (PMID 41564380, 2026). "Few researches study on the effect of ACSL3 on liver disease." (PMID 37957550, 2023).
non-small cell lung carcinoma (3 papers, 2019 to 2023). A group of at least three distinct histological types of lung cancer, including non-small cell squamous cell carcinoma, adenocarcinoma, and large cell carcinoma. "Recent evidence in non-small cell lung cancer suggests that ACSL3 is important in maintaining the channeling of extracellularly-derived lipids to FAO." (PMID 31344914, 2019). "We previously showed that KRAS drives the transcriptional upregulation of ACSL3 and ACSL4 in non-small cell lung cancer, and that this can be prevented by the inhibition of the mammalian target of rapamycin complex 1 (mTORC1)." (PMID 31344914, 2019).
Obesity (3 papers, 2016 to 2023). Accumulation of substantial excess body fat. "Since Nisch regulates the expression of ACSL3, PPARα, and CHREBP, activation of PPARα/AMPK expression of Nisch may be a novel approach to inhibit obesity and hepatic steatosis, and thus, Nisch may play an important role in obesity." (PMID 35163298, 2022).
pancreatic ductal carcinoma (3 papers, 2022 to 2024). "Knockdown of ACSL3 impeded pancreatic ductal carcinoma progression, which regulated fibrotic and ratio of immune cells in TIME." (PMID 38743344, 2024). "ACSL3, which is unique to the fibrotic alveoli, is elevated in pancreatic ductal carcinoma, where it correlates with increased fibrosis." (PMID 35852874, 2022). "Studies found that ACSL3 is upregulated in human pancreatic ductal adenocarcinoma (PDAC), and the deletion of ACSL3 could delay PDAC progression and reduce fibrosis in mice." (PMID 36172157, 2022).
triple-negative breast carcinoma (3 papers, 2019 to 2023). An invasive breast carcinoma which is negative for expression of estrogen receptor (ER), progesterone receptor (PR), and human epidermal growth factor receptor 2 (HER2). "Mechanistically, oleic acid secreted from adipocytes inhibited lipid peroxidation and ferroptosis of triple-negative breast cancer cells in the presence of ACSL3." (PMID 35659320, 2022). "On the other hand, in triple-negative breast cancer, ACSL3 is significantly reduced, resulting in high FAO/low lipid droplet abundance, and serves as a poor prognosis marker of the triple-negative breast cancer metastatic potential." (PMID 31344914, 2019). "In fact, in triple-negative breast cancer, ACSL3 interacts with the pro-metastatic protein CUB domain-containing protein 1 (CDCP1)." (PMID 31344914, 2019). "ACSL3, although found to be upregulated in women with ER-negative breast cancer, has also been shown to be downregulated in triple-negative breast cancer." (PMID 31344914, 2019).
atherosclerosis (2 papers, 2020 to 2024). A disease characterized by the build-up of fatty material and calcium deposition in the arterial wall resulting in partial or complete occlusion of the arterial lumen. "Of all candidate genes for Ath30, Crygc and Mogat1showed a negative correlation with atherosclerosis in their hepatic transcript levels, Cyp27a1 showed a negative and Acsl3 a positive correlation with atherosclerosis in aortic transcript levels." (PMID 33109727, 2020).
colon cancer (2 papers, 2022). "It has been previously shown that ACSL3 activity was responsible for the protective effect of oleic acid against ferroptosis induction in colon cancer cells independently of lipid droplet synthesis." (PMID 36192773, 2022).
colorectal cancer (2 papers, 2016 to 2025). A primary or metastatic malignant neoplasm that affects the colon or rectum. "High ACSL3 expression has been detected in a variety of cancers and is correlated with a poor prognosis in patients with these diseases, and ACSL3-mediated fatty acid oxidation is required for TGFβ1-induced EMT and metastasis in colorectal carcinoma." (PMID 40299526, 2025).
fibrosarcoma (2 papers, 2018 to 2019). A malignant mesenchymal fibroblastic neoplasm affecting the soft tissue and bone. "Immunohistochemical staining revealed that ACSL3 is moderately to highly expressed in human fibrosarcomas, leiomyosarcomas and rhabdomyosarcomas." (PMID 31344914, 2019). "In this study, immunohistochemical screening of multiple soft tissue tumour arrays revealed that ACSL3 and ACSL4 were highly, but differentially, expressed in a subset of leiomyosarcomas, fibrosarcomas and rhabdomyosarcomas, with consistent cytoplasmic and granular stainings of tumour cells." (PMID 29450800, 2018).
glioblastoma (2 papers, 2015 to 2016). The most malignant astrocytic tumor (WHO grade IV). "Finally, ACSL3 expression is elevated in the highly tumorigenic U87 human glioblastoma cell line and cells derived from tumorigenic primary glioblastoma xenografts (Mayo 22) compared with the less tumorigenic U373 glioma cells." (PMID 25866768, 2015).
glioma (2 papers, 2021 to 2022). A benign or malignant brain and spinal cord tumor that arises from glial cells (astrocytes, oligodendrocytes, ependymal cells). "Future studies may discover more meaningful details about the changes in function of ACSL3 for glioma." (PMID 36507355, 2022). "Similarly, survival probability in hepatocellular carcinoma was reliably predicted by a glioma prediction model (ACSL3, ACSL6, ACACA, G6PD, SLC1A5, SLC7A11 and VDAC2) and by a risk model with a strong overlap with the genes in the glioma models (G6PD, HMOX1, LOX, SLC7A11, STMN1/Stathmin 1)." (PMID 34926298, 2021).
prostate tumors (2 papers, 2011 to 2020). "The literature has reported that the expression of ACSL3 is significantly higher in metastatic prostate tumors than in primary prostate tumors." (PMID 33585230, 2020). "In this sense, ACSL3 seems to be slightly up-regulated in primary prostate tumors and strongly repressed in metastatic cancer." (PMID 21829708, 2011). "Data on ACSL3, MCCC2 and ENDOD1 protein expression is available for 3 normal tissue samples and 11 prostate tumors." (PMID 21829708, 2011).
renal carcinoma (2 papers, 2022 to 2024). A carcinoma arising from the epithelium of the renal parenchyma or the renal pelvis. "As shown by our results, ACSL3 expression was significantly downregulated in ccRCC tissues and renal cancer cell lines." (PMID 36338658, 2022). "The expression level of ACSL3 was significantly reduced in ccRCC tissues, and its mRNA and protein expression were also significantly lower in both renal cancer cell lines." (PMID 36338658, 2022). "The distinct metabolic profile of renal cancer is intimately associated with its sensitivity to ferroptosis, with multiple molecular mechanisms implicated in the regulation of ferroptosis in renal cancer, including PDIA4, GPX4, KLF2, ACSL3, and AIM2." (PMID 39092291, 2024).
Anxiety (1 paper, 2024). Intense feelings of nervousness, tension, or panic often arise in response to interpersonal stresses. "Targeting ACSL3 will offer an innovative approach for treating AD-related depression and anxiety." (PMID 39532829, 2024). "Upregulation of ACSL3 via adenovirus in aged 3xTg-AD mice led to increased protein levels of brain-derived neurotrophic factor (BDNF) and vascular endothelial growth factor C (VEGF-C) (via brain histology, capillary-based immunoassay), resulting in alleviation of depression and anxiety symptoms." (PMID 39532829, 2024).
cardiomyopathy (1 paper, 2012). A disease of the heart muscle or myocardium proper. "It was not shown if the elevated expression of ACSL3 is cause or the result of the cardiomyopathy." (PMID 22761652, 2012).
cerebrovascular diseases (1 paper, 2025). "The ACSL family consists of five isoforms—ACSL1, ACSL3, ACSL4, ACSL5, and ACSL6—each of which has been implicated in the pathogenesis, treatment, and prognosis of diverse conditions, including metabolic disorders, cancers, cardiovascular and cerebrovascular diseases, and other clinical conditions." (PMID 41288931, 2025). "While numerous studies have investigated targeting ACSL4 to mitigate brain injury in cerebrovascular disease, the roles of ACSL1 and ACSL3 as key regulators of ferroptosis remain underexplored." (PMID 41288931, 2025).
clear cell carcinoma (1 paper, 2022). "ACSL3 overexpression has been discovered in a number of different types of cancer and is linked with a poor prognosis, the polar opposite of clear cell carcinoma." (PMID 36338658, 2022).
diabetic cardiomyopathy (1 paper, 2012). Diabetic cardiomyopathy is a disorder of the heart muscle in people with diabetes. "In rats, increased mRNA expression of ACSL3 was observed in the progression of diabetic cardiomyopathy in the myocardium." (PMID 22761652, 2012).
ductal adenocarcinomas (1 paper, 2020). "Our analysis evidenced that the mRNA level of ACSL3 is higher in primary ductal adenocarcinomas and metastasis compared to healthy epithelium." (PMID 33127675, 2020).
endometriosis (1 paper, 2025). The growth of functional endometrial tissue in anatomic sites outside the uterine body. "There has been limited research on the roles of ACSL5, PLA2G4A, EHHADH, GPAM, PLA2G15, SULT2A1, and ACSL3 in endometriosis, highlighting the necessity for further investigation to elucidate their contributions to its pathogenesis." (PMID 40527850, 2025).
food allergy (1 paper, 2024). Gastrointestinal disturbances, skin eruptions, or shock due to allergic reactions to allergens in food. "Furthermore, methylation of ACSL3 has also been identified as a signature predictive of clinical food allergy in children." (PMID 38585273, 2024).
hyperlipidemia (1 paper, 2022). "The red raspberry extract (RRE) can significantly reduce the level of blood lipid in mice with hyperlipidemia, and Acsl3 is one of the regulatory genes, accelerating the conversion of triglyceride to fatty acid." (PMID 36147301, 2022).
Insulin resistance (1 paper, 2020). Increased resistance towards insulin, that is, diminished effectiveness of insulin in reducing blood glucose levels. "Thus, decreased expression of ABCG1, ABCA1, and ACSL3 could impair insulin secretion and lead to insulin resistance." (PMID 32612641, 2020).
lung diseases (1 paper, 2023). "Statistical analyses demonstrated that mRNA expression of ACSL1, ACSL3 and ACSL4 in lung and airway epithelial cells among lung diseases." (PMID 36639836, 2023).
myeloma (1 paper, 2025). "All of the five human ACSL family members had negative Chronos scores (suggesting they support myeloma cell line growth and survival), and ACSL3 and ACSL4 were in the top 25% most essential fatty acid metabolism‐related genes." (PMID 39853696, 2025). "ACSL1, ACSL3, ACSL4, and ACSL5 are expressed in primary myeloma cells and supportive of myeloma cell fitness, suggesting that broad targeting of the ACSLs could be impactful for MM patients." (PMID 39853696, 2025). "Cancer Dependency Map (DepMap) data showed that all five ACSLs have negative Chronos scores, and ACSL3 and ACSL4 were among the top 25% Hallmark Fatty Acid Metabolism genes that support myeloma cell line fitness." (PMID 39853696, 2025).